SCGB2A2 (secretoglobin family 2A member 2)
Synonyms: MGB1; UGB2; MGC71974; PSBP1
Tractability: Antibody: UniProt places it where antibodies can reach, with high confidence; UniProt predicts a signal peptide or a membrane-spanning region; its Gene Ontology location is reachable by antibodies, with medium confidence.
Gene: Protein-coding gene on chromosome 11 (62,270,158 to 62,273,160, forward strand). Ensembl gene ENSG00000110484.
Subcellular location: Secreted
Gene Ontology:
Molecular function: protein binding
Biological process: androgen receptor signaling pathway
Cellular component: extracellular region
Genetic constraint (gnomAD): Loss-of-function variants: 10 observed, 8.22 expected, observed/expected ratio (o/e) 1.22, 90% interval 0.74 to 1.85. That is too few expected variants to judge how well the gene tolerates losing a copy. Missense variants: 101 observed, 101.31 expected, observed/expected ratio (o/e) 1, 90% interval 0.85 to 1.18. Synonymous variants: 36 observed, 38.88 expected, observed/expected ratio (o/e) 0.93, 90% interval 0.71 to 1.22.
Homologues: Orthologues: chimpanzee SCGB2A2 (98% identical), pig PHEROC (56% identical), dog SCGB2A2 (49% identical), mouse Scgb2a2 (42% identical), rat Scgb2a1 (41% identical), rat Scgb2a1 (39% identical). Paralogues in human: SCGB2A1 (58% identical).
Diseases named in the same sentence as SCGB2A2 in open-access papers:
SCGB2A2 is named in the same sentence as 43 diseases in open-access papers, as found by Europe PMC text mining. Sharing a sentence is not in itself a finding about the gene and the disease. The quoted sentences say what the papers report.
breast carcinoma (55 papers, 2002 to 2026). "Among them, AZGP1 and CRISP3 are associated with breast cancer invasiveness, while SCGB2A2 and SCGB1D2 serve as common markers for disseminated tumor cells (DTCs)." (PMID 40838787, 2025). "In the CUP-LM case of our previous study, we discovered seven circulating tumor cells in CSF showing SCGB2A2 expression and discussed the diagnostic value of SCGB2A2 for tumor origin of breast cancer and salivary gland cancer." (PMID 38274387, 2024). "The epithelial marker CK19 and the breast cancer related marker SCGB2A2 were significantly associated with shorter OS in the metastatic patients." (PMID 36831613, 2023). "The highly specific epithelial (CK19) and breast cancer specific (SCGB2A2) marker were significantly associated with shorter overall survival." (PMID 36831613, 2023). "Human mammaglobin-A (SCGB2A2) is a secretory protein with an unknown function that is used as a diagnostic marker for breast cancer." (PMID 36980510, 2023). "Feature map of a representative sample from a BRCA (breast cancer) patient assigns the 2 out of 3 biomarker genes, SCGB2A2 and PIP, with the top 10 feature weights." (PMID 40662781, 2025). "SCGB2A1, SCGB2A2, and PIP genes showed association with breast cancer, in addition to S100A14, S100A16, and CEACAM5, which were associated with colorectal cancer as well." (PMID 36428760, 2022). "Mammaglobin 1 (MGB1), also known as mammaglobin A or SCGB2A2, is a member of the secretoglobin family located on a genomic region frequently amplified in breast cancer chromosomes 11q12.3–137,8." (PMID 35945910, 2022). "Conversely, the DCB gene SCGB2A2 was downregulated in TNBC but upregulated in HR+ breast cancer samples." (PMID 33883548, 2021). "When we applied heteroDE to breast cancer samples, we identified 7 cfRNA biomarkers (SCGB2A2, CASP14, FABP7, CRABP2, VGLL1, SERPINB5, TFF1), 3 of which (FABP7, SCGB2A2, CASP14) overlap with previously identified DCB genes." (PMID 33883548, 2021). "Overexpression of mammaglobin 1 (SCGB2A2)/lipophilin B (SCGB1D2) and PIP is linked to good prognosis in ovarian and breast cancer." (PMID 31360859, 2018). "SCGB2A2, identified as a candidate causal gene for MY in both fine-mapping and MR analysis, is a breast-specific member of the SCGB gene family and a marker for breast cancer in human." (PMID 41484547, 2026). "SCGB2A2 is also glycosylated and has beeninvestigated for its role in breast cancer." (PMID 35549755, 2022). "In the present study, the transcript levels of a 6-gene panel (CCNE2, PPIC, MAL2, EMP2, HJURP, and SCL6A8) previously published as candidate CTC markers, and of epithelial cell lineage-specific (EpCAM, CK19) and breast cancer-specific (SCGB2A2) markers were assessed." (PMID 36074219, 2022). "Interestingly, when we evaluated the expression of SCGB2A2 (a classical marker of breast cancer), seven CTCs from P8 had high expression levels, whereas other CSF‐CTCs had little to no expression, showing the advantage of scRNA‐seq over bulk RNA‐seq or IHC." (PMID 33377642, 2020). "MATN2 and SCGB2A2 are upregulated in ovarian cancer; S100P is upregulated in prostate cancer, invasive ductal carcinomas, and pancreatic cancer; LDHB is a biomarker for triple negative breast cancer; and TNC is associated with Tamoxifen resistance in breast cancer." (PMID 27449296, 2016). "The six-gene panel was superior to the commonly used marker genes for epithelial breast cancer CTCs, EpCAM and human mammaglobin A (SCGB2A2), both in samples from patients with early and advanced breast cancer." (PMID 36831613, 2023). "Previous studies show that MGP promotes the breast cancer proliferation, SCGB2A2 and TFF3 can be viewed a valuable predictive biomarker in breast cancer." (PMID 38096269, 2023). "The markers SCGB2A2, EpCAM, SLC6A8 and PPIC were detectable in about half of the metastatic breast cancer samples." (PMID 36831613, 2023).
breast carcinoma (continued). "In a recent study, using RT-qPCR, two panels of transcripts related to the presence of CTCs (Panel 1: CK19, EpCAM, SCGB2A2 and Panel 2: EMP2, SLC6A8, HJURP, MAL2, PPIC and CCNE2), in two cohorts of breast cancer patients (metastatic and early), were evaluated." (PMID 37046848, 2023). "Using mRNA sequencing and proteomic data from TCGA and CPTAC of 24 different solid tumors, we identified six potential genes that are specifically upregulated in breast carcinoma: NAT1, MGP, SCGB2A2, LMX1B, TFAP2B, and TRPS1." (PMID 36284362, 2022). "Mammaglobin A (SCGB2A2) and lipophilin B (SCGB1D2) expression was analyzed by northern blot in a panel of 4 matched breast cancer/normal breast tissue pairs." (PMID 16603086, 2006). "Mammaglobin A (SCGB2A2) and lipophilin B (SCGB1D2), two members of the secretoglobin superfamily, are known to be co-expressed in breast cancer, where their proteins form a covalent complex." (PMID 16603086, 2006). "In our present study, we evaluated two panels of transcripts related with the presence of circulating tumor cells (CTCs) (Panel 1: CK19, EpCAM, SCGB2A2 and Panel 2: EMP2, SLC6A8, HJURP, MAL2, PPIC and CCNE2) in two cohorts of breast cancer patients (metastatic and early)." (PMID 36831613, 2023). "While SCGB2A2 and SCGB1D2 are reported as markers of breast cancer, their roles in human brain have not been exhaustively investigated." (PMID 40033360, 2025). "Indeed, EMP2 and PPIC transcripts in spiked blood samples indicated the presence of Hs579T breast cancer cells; in contrast, the analysis of the epithelial markers EpCAM, CK19 and SCGB2A2 alone would not have detected these hormone receptor and HER2-negative cells." (PMID 36831613, 2023).
lung carcinoma (4 papers, 2006 to 2021). "The expression of SCGB1D1 (LIPA), SCGB2A1 (MGB2), and SCGB2A2 (MGB1) has been shown to be upregulated in human lung cancers." (PMID 21385388, 2011).
ovarian carcinoma (4 papers, 2010 to 2019). A malignant neoplasm originating from the surface ovarian epithelium. "The overexpression of SCGB2A2 is positively correlated with the FIGO stage, the tumor grade and the mitotic index of the ovarian cancer." (PMID 31288815, 2019).
salivary gland cancer (2 papers, 2020 to 2024). A primary or metastatic malignant neoplasm that affects the major or minor salivary glands. "In addition, SCGB2A2 is also associated with salivary gland cancer." (PMID 33377642, 2020).
triple-negative breast carcinoma (2 papers, 2016 to 2025). An invasive breast carcinoma which is negative for expression of estrogen receptor (ER), progesterone receptor (PR), and human epidermal growth factor receptor 2 (HER2). "However, SCGB2A2 sensitivity is limited particularly for detecting triple-negative breast cancer; moreover, it has been reported to be present in female reproductive tract tumors such as cervix, endometrium, ovary as well as certain salivary gland tumors and skin cancer." (PMID 40474021, 2025).
ovarian tumor (1 paper, 2019). "The role of SCGB2A2 in patho-physiology of the ovarian tumor was identified." (PMID 31288815, 2019).
tumor (32 papers, 2006 to 2025). "SCGB2A2 provided clues for the tumor origin of the CUP-LM patient, however, the patient was lost to follow up and a definitive conclusion failed to make." (PMID 38274387, 2024). "Sixty-three genes defining tumor clusters were selected and SCGB2A2 expression was positive in eight CSF tumor cells." (PMID 38274387, 2024). "High-risk prognostic genes BMP4, CELSR3, GPRC5C, and RUNDC3B, highly expressed in Epithelial Cells, CCBE1 showed expression in Leydig cells, SCGB2A2 highly expressed in Epithelial Cells and Cancer cells, suggesting that Epithelial cell play an important role in tumor growth and initiation." (PMID 37985782, 2023). "In the present study, tumor cells were observed to be reduced in BM and highly expressed MUC1, SCGB2A2, FN1, BGN, and PEG10." (PMID 37470685, 2023). "Immunohistochemistry of primary tumor tissue was performed for eight proteins: COL6A6, DCD, GBP4, KLHL41, KRT9, PIP, SCGB1D2, SCGB2A2." (PMID 34757537, 2022). "Mammaglobin A (SCGB2A2) and lipophilin B (SCGB1D2) expression were analyzed by dot blot analysis using Clontech's "Matched Tumor/Normal Array" (MTNA) and "Cancer Profiling Array I" (CPA) for each gene." (PMID 16603086, 2006). "Likewise, our data showed HER2low TNBC actively participated in activities with regard to tumor metabolism and growth pathways with MUCL1, PTN, SCGB2A2 and APOD highly expressed, revealing an increased metabolic and proliferative capacity contained." (PMID 36998014, 2023). "There are also a number of samples that appear to have relatively high tumor content (>1%) for SCGB2A2 and FABP7, but for which the genes are not detected in cfRNA, suggesting that other factors beyond tumor tissue expression may influence the detectability of a given biomarker in circulation." (PMID 33883548, 2021).
cancer (16 papers, 2006 to 2025). A tumor composed of atypical neoplastic, often pleomorphic cells that invade other tissues. "PROS1 is highly expressed in Cancer Cells, Endothelial Cells, Fibroblasts, and M1 Macrophages, and; SCGB2A2 is highly expressed in Cancer Cells, Epithelial Cells, and Granulosa, TRO is expressed in Fibroblasts." (PMID 37985782, 2023). "The detection of as few as 10 SKBR3 cancer cells isolated from a peripheral blood matrix (5 mL) was possible using the markers CK19, SCGB2A2, EpCAM, EMP2, MAL2 and PPIC." (PMID 36831613, 2023).
SCGB2A2 also shares sentences with these, for which no sentence is quoted: breast tumor (5 papers); gynecological cancer (3); gynecological tumors (3); infection (3); cervical cancer (2); endometrial cancer (2); endometriosis (2); invasive ductal carcinoma (2); melanoma (2); pancreatic cancer (2); prostate carcinoma (2); adenocarcinoma (1); adenomyosis (1); Autoimmunity (1); bone metastasis (1); cervical adenocarcinoma (1); cholangiocellular carcinomas (1); colon cancers (1); endometrioid adenocarcinoma (1); endometrium carcinoma (1); glioblastoma (1); ichthyosis (1); invasive breast carcinoma (1); metastatic carcinoma (1); metastatic disease (1); Nasal polyposis (1); nasal polyps (1); pheochromocytoma (1); rectal tumor (1); salivary gland tumors (1).
A further 5 diseases each share a sentence with SCGB2A2 in 1 paper.